GANAB (glucosidase II alpha subunit)
Description:
Catalytic subunit of glucosidase II that cleaves sequentially the 2 innermost alpha-1,3-linked glucose residues from the Glc(2)Man(9)GlcNAc(2) oligosaccharide precursor of immature glycoproteins. Required for PKD1/Polycystin-1 and PKD2/Polycystin-2 maturation and localization to the cell surface and cilia.
Synonyms: G2AN; KIAA0088; GluII; GIIA; GIIalpha; PKD3
Tractability: Small molecule: it belongs to a druggable protein family. Antibody: UniProt predicts a signal peptide or a membrane-spanning region. PROTAC: ubiquitination databases record sites on it; its protein half-life has been measured; a small molecule that binds it is known.
Target class: Enzyme; Hydrolase
Gene: Protein-coding gene on chromosome 11 (62,624,824 to 62,646,726, reverse strand). Ensembl gene ENSG00000089597.
Subcellular location: Endoplasmic reticulum; Golgi apparatus; Melanosome
Subcellular location (Human Protein Atlas): Endoplasmic reticulum
Pathways (Reactome):
Metabolism of proteins: Calnexin/calreticulin cycle; N-glycan trimming in the ER and Calnexin/Calreticulin cycle
Cell-Cell communication: Regulation of CDH1 posttranslational processing and trafficking to plasma membrane
Disease: Maturation of spike protein
Gene Ontology:
Molecular function: alpha-glucosidase activity; Glc2Man9GlcNAc2 oligosaccharide glucosidase activity; glucan 1,3-alpha-glucosidase activity; protein binding; RNA binding; carbohydrate binding; hydrolase activity, hydrolyzing O-glycosyl compounds
Biological process: N-glycan processing; carbohydrate metabolic process
Cellular component: endoplasmic reticulum; extracellular exosome; glucosidase II complex; intracellular membrane-bounded organelle; melanosome; membrane; endoplasmic reticulum lumen; Golgi apparatus
Genetic constraint (gnomAD): Loss-of-function variants: 30 observed, 103.96 expected, observed/expected ratio (o/e) 0.29, 90% interval 0.22 to 0.39. The upper end of that interval is the gene's LOEUF score, 0.39, which puts it in group 1 of 6, group 1 being the genes least tolerant of losing a copy. Missense variants: 805 observed, 1,101.8 expected, observed/expected ratio (o/e) 0.73, 90% interval 0.69 to 0.77. Synonymous variants: 414 observed, 414.05 expected, observed/expected ratio (o/e) 1, 90% interval 0.92 to 1.09.
Gene-disease validity (ClinGen):
ClinGen rates the evidence that GANAB causes each of these diseases.
polycystic kidney disease 3 with or without polycystic liver disease (autosomal dominant): Definitive. Any autosomal dominant polycystic kidney disease in which the cause of the disease is a mutation in the GANAB gene.
Homologues: Orthologues: chimpanzee GANAB (99% identical), macaque GANAB (99% identical), dog GANAB (93% identical), mouse Ganab (92% identical), pig GANAB (91% identical), rat Ganab (91% identical), guinea pig GANAB (88% identical), tropical clawed frog ganab (68% identical), zebrafish ganabb (64% identical), zebrafish ganaba (63% identical), Caenorhabditis elegans aagr-2 (20% identical). Paralogues in human: GANC (48% identical), MGAM (27% identical), SI (27% identical), GAA (27% identical), MGAM2 (24% identical), MYORG (13% identical).
Diseases named in the same sentence as GANAB in open-access papers:
GANAB is named in the same sentence as 48 diseases in open-access papers, as found by Europe PMC text mining. Sharing a sentence is not in itself a finding about the gene and the disease. The quoted sentences say what the papers report.
polycystic kidney disease (10 papers, 2018 to 2025). A usually autosomal dominant and less frequently autosomal recessive genetic disorder characterized by the presence of numerous cysts in the kidneys leading to end-stage renal failure. "With the increase in polycystic kidney disease caused by GANAB gene mutations in recent years, a suitable animal model is still needed to further explore the pathogenic role of this gene." (PMID 32550232, 2020). "Polycystic kidneys, also a part of the PD syndrome, were recently associated with a loss of GANAB (subunit α of glucosidase II), which is required for maturation of polycystin proteins and their localization to the cell surface." (PMID 29788428, 2018). "GANAB has been implicated in the development of autosomal-dominant polycystic kidney and liver disease." (PMID 30333007, 2018). "The patients in this family all suffered from polycystic kidney with liver disease, consistent with earlier findings that the phenotype caused by GANAB mutations usually manifests with polycystic liver disease (PLD)." (PMID 30333007, 2018). "Additionally, GANAB and HNF1β mutations may lead to mild polycystic kidney disease." (PMID 40507770, 2025). "ADPKD is primarily caused by mutations in the polycystic kidney disease genes 1 or 2 (PKD1 or PKD2), and less commonly by variants in other genes such as glucosidase II alpha subunit (GANAB), which have been associated with milder renal phenotypes and concurrent polycystic liver disease." (PMID 41181723, 2025). "As p.Pro123Ala was predicted to be a disease-causing mutation by three tools and p.Ile764Met was predicted to be benign by PolyPhen-2, the possibility that p.Leu727Pro in PKD1 and p.Pro123Ala in GANAB co-contribute to the development of polycystic kidney with liver disease cannot be excluded." (PMID 30333007, 2018). "For genetic workup, further polycystic kidney disease genes were analyzed, PKD1 and PKD2 in 12, HNF1B in 8, and DZIP1L and GANAB in 5 children each without detection of variants." (PMID 35812281, 2022).
polycystic liver disease (10 papers, 2018 to 2025). "In polycystic liver disease, miR-345 has been shown to reduce proliferation, possibly by downregulating GluII subunits like GANAB which encodes the α-subunit, supporting the concept of post-transcriptional regulation as a selective therapeutic strategy." (PMID 41465297, 2025). "First, GANAB is the only gene that has been shown to cause polycystic liver disease in patients with ADPLD or ADPKD." (PMID 33097077, 2020). "However, genetic mutations of GANAB are the only ones that have been shown to cause polycystic liver disease in patients affected by ADPLD or ADPKD as a kind of pathogenic continuum between these two forms." (PMID 35806376, 2022). "Mutations in PRKCSH and GANAB, human orthologs of GTB1 and ROT2, are linked to polycystic liver disease." (PMID 32994210, 2020). "Heterozygous GANAB mutations that can cause autosomal dominant polycystic kidney disease (ADPKD) and polycystic liver disease (PLD) have been described previously, but their roles in ADPKD and PLD are largely unknown." (PMID 32550232, 2020). "Therefore, mutations in the GANAB gene can cause ADPKD and polycystic liver disease." (PMID 32550232, 2020). "In the polycystic liver disease condition, the hepatocystin fails to assemble with GANAB during carbohydrate processing, leading to altered cellular proliferation and differentiation." (PMID 35879690, 2022).
autosomal dominant polycystic kidney disease (9 papers, 2017 to 2025). Autosomal dominant form of polycystic kidney disease. "Variants in the GANAB gene have been implicated in autosomal dominant polycystic kidney disease, a condition characterized by the formation of renal cysts leading to progressive kidney dysfunction." (PMID 40770708, 2025). "It should be noted that mutations in GANAB have been found to cause the life-threatening autosomal-dominant polycystic kidney disease." (PMID 36450445, 2023). "Autosomal dominant polycystic kidney disease (ADPKD), the commonest inherited kidney disease, is generally caused by heterozygous mutations in PKD1, PKD2, or GANAB (PKD3)." (PMID 30333007, 2018). "Autosomal dominant polycystic kidney disease (ADPKD): ADPKD is the most common inherited progressive renal disease caused by the mutation of two major genes, PKD1 and PKD2, and the rare genes, GANAB and DNAJB11." (PMID 37445416, 2023). "Several recent studies reported that autosomal dominant polycystic kidney disease (ADPKD) is mainly caused by mutations in the PKD1 and PKD2 genes and rarely by mutations in the GANAB gene." (PMID 32550232, 2020).
Kidney Cyst (5 papers, 2020 to 2025). Abnormal fluid filled sac within the kidney, either acquired or congenital. "In patients with the diagnosis of PKHD1, ALG8, and GANAB variants, kidney cysts tend to be less destructive than PKD1 and PKD2 with relatively preserved kidney contours." (PMID 35778421, 2022). "Our patient was also found to have VUS c.2622C>G, p.Phe874Leu in the GANAB gene, which explained the presence of kidney cysts." (PMID 40428323, 2025). "DY1591 I-2 had GANAB p.Val4_Ala5del variant and renal ultrasonography showed bilateral multiple kidney cysts without liver cysts as well as preserved kidney contour at the age of 38." (PMID 35778421, 2022). "Of the eight patients with likely pathogenic heterozygous GANAB variants, seven patients presented with ADPLD and three patients had 1–3 kidney cysts, while in the remaining patients no kidney cysts could be detected." (PMID 33097077, 2020).
cyst (4 papers, 2021 to 2024). A sac-like closed membranous structure that may be empty or contain fluid or amorphous material. "No other pathogenic variants were found in other ADPKD-associated genes (PKDH1, GANAB, ACE, etc,) or related to cyst progression." (PMID 35327948, 2022).
cystic kidney disease (4 papers, 2019 to 2025). A congenital or acquired kidney disorder characterized by the presence of renal cysts. "Here, we describe a case of a dual mutation in PKD1 and GANAB genes with an early clinical presentation in a 12-year-old adolescent girl with renal cyst formation and nephrolithiasis; and discuss impacts of dual mutation on the severity of the disease." (PMID 30792735, 2019). "In this case, the nonsense GANAB mutation resulted in symptomatic nephrolithiasis resulting in clinical evidence of bilateral renal cysts at the age of 12, contradicting the previous data suggesting the mutation results in subclinical to mild disease." (PMID 30792735, 2019).
gastric cancer (4 papers, 2020 to 2024). A primary or metastatic malignant neoplasm involving the stomach. "In addition, gastric cancer patients were likely to have mutations in CDH1, ACTRT1, GANAB, and CDH10 genes in the High-CCDC80 group." (PMID 38872096, 2024).
melanoma (4 papers, 2018 to 2022). A malignant, usually aggressive tumor composed of atypical, neoplastic melanocytes. "GANAB was among proteins most enriched in acidic exosomes implicated in melanoma progression, with high expression levels associated with poor prognosis." (PMID 32664474, 2020). "In addition, it was found that higher expression levels of GANAB were intimately associated with poor prognosis in melanoma." (PMID 35879690, 2022). "High expression of GANAB was significantly correlated with poor prognosis in melanoma." (PMID 32306508, 2020).
autosomal dominant polycystic liver disease (3 papers, 2017 to 2024). An autosomal dominant inherited condition characterized by many cysts of various sizes scattered throughout the liver. "They report that GANAB accounts for ~0.3% of total ADPKD and it is associated with a milder manifestation of PKD and autosomal dominant polycystic liver disease (ADPLD)." (PMID 29326913, 2017). "Recently a third causative gene in ADPKD and autosomal dominant polycystic liver disease (ADPLD) was identified to be GANAB, responsible for 0.3% of all ADPKD." (PMID 30803434, 2019).
liver cysts (3 papers, 2020 to 2023). "The causative genes of severe liver cysts were five variants in PKD1, one variant in GANAB, and one variant in PKHD1." (PMID 36833371, 2023). "In silico and RT-PCR analyses show that the GANAB gene is expressed approximately equally in the human kidneys and liver, that the GANAB protein mainly plays a role in assisting PC1 and PC2 protein maturation, and that GANAB mutations cause kidney and liver cysts via loss of these functions." (PMID 32550232, 2020).
urothelial carcinoma (3 papers, 2022 to 2025). A malignant neoplasm derived from the transitional epithelium of the urinary tract (urinary bladder, ureter, urethra, or renal pelvis). "The poor prognosis of urothelial carcinoma relates to higher expression of Glucosidase II α-subunit (GANAB protein), which is a regulator of glycosylation that could be used as a prognostic biomarker for urothelial carcinoma." (PMID 38372785, 2024).
end-stage renal disease (2 papers, 2020 to 2025). "The GANAB gene mutation found in this patient is typically associated with mild kidney disease; however, according to the Mayo Clinic Imaging Classification (MIC) for ADPKD, our patient falls under Classification 1E, which is predictive of rapid progression to end-stage renal disease (ESRD)." (PMID 40134995, 2025).
asthma (1 paper, 2021). "GANAB and CANX belong to endoplasmic reticulum protein chaperones, which cooperate with CALR to regulate endoplasmic reticulum stress in osteoarthritis and asthma, respectively." (PMID 34910788, 2021).
bladder cancer (1 paper, 2022). "Interestingly, we found that siGANAB synergistically enhanced the effects of tunicamycin in our in vitro models, suggesting that GANAB might serve as a promising therapeutics target for bladder cancer that warrant further studies." (PMID 35879690, 2022). "To determine whether GANAB was involved in the regulation of ERS signaling, we conducted experiments to quantitate the transcriptional activation of ATF6 by using siRNA-mediated GANAB knockdown in bladder cancer cell lines with/without tunicamycin (Tm) stimulation." (PMID 35879690, 2022).
demyelinating disease (1 paper, 2023). A broad group of disorders that affect the myelin sheaths that cover the neurons. "Biological observations have indicated some interesting molecules, including vitamin D, Neurofilament light (NfL), IFP35, and GANAB as emerging biomarkers in demyelinating diseases." (PMID 37685453, 2023).
knee osteoarthritis (1 paper, 2010). "GANAB is an ER-enzyme that has profound effects on the early events of glycoprotein metabolism, and has been recently proposed as biomarker for detecting mild human knee osteoarthritis." (PMID 20626852, 2010).
nephrolithiasis (1 paper, 2019). The presence of a calculus in the pelvis of the kidney; this is most often composed of mineral salts and proteins. "In summary, the presented case is the first reported pediatric case with dual mutation (PKD1 and GANAB) and nephrolithiasis." (PMID 30792735, 2019).
ovarian carcinoma (1 paper, 2023). A malignant neoplasm originating from the surface ovarian epithelium. "Herein, we have confirmed that the expression of GANAB is markedly increased in ovarian cancer tissues." (PMID 37781028, 2023). "Consistently, GANAB overexpression has the potential to reverse the reduced ovarian cancer cell proliferation, migration, and invasion ability induced by STAT3 deficiency." (PMID 37781028, 2023). "As a result, YTHDC1 knockdown significantly promoted ovarian cancer progression in vivo and in vitro and GANAB knockdown markedly suppressed ovarian cancer progression in vivo and in vitro, however, silencing GANAB abrogated shYTHDC1-induced tumor promotion." (PMID 37781028, 2023). "Mechanistically, low expression of YTHDC1 promotes ovarian cancer tumorigenesis via PIK3R1/STAT3/GANAB axis." (PMID 37781028, 2023). "Furthermore, the GEO datasets confirmed that GANAB mRNA level were elevated in ovarian cancer, which was also verified by IHC staining." (PMID 37781028, 2023). "Moreover, a lower expression level of PIK3R1 induced by YTHDC1 knockdown leads to activation of STAT3 signaling, which further promotes GANAB expression in the nucleus, followed by an increase of GANAB-mediated N-glycan biosynthesis in ovarian cancer cells, which promotes ovarian cancer progression." (PMID 37781028, 2023). "As expected, GEPIA database analysis revealed that there was a positive correlation between GANAB and STAT3 expression in ovarian cancer." (PMID 37781028, 2023).
schizophrenia (1 paper, 2023). A major psychotic disorder characterized by abnormalities in the perception or expression of reality. "Further studies indicated that ERVW-1 induced ER stress and ER vacuolization and that GANAB participated in those processes caused by ERVW-1, showing the potential mechanism of aberrant protein homeostasis in the ER in the pathogenesis of schizophrenia." (PMID 37376599, 2023). "Interestingly, we also identified abnormal expression of GANAB, a catalytic subunit of glucosidase II involved in glycosylation, in individuals with schizophrenia." (PMID 37376599, 2023). "In this paper, we investigated the potential link between GANAB and schizophrenia." (PMID 37376599, 2023). "Therefore, we propose that ATF6, XBP1, and GANAB might serve as potential serum biomarkers of schizophrenia." (PMID 37376599, 2023). "In conclusion, GANAB participates in the ERVW-1-induced ATF6-mediated UPR pathway, leading to ER stress and contributing to the pathogenesis of schizophrenia." (PMID 37376599, 2023). "In summary, there was aberrant expression of ATF6, XBP1, and GANAB in the serum of schizophrenic patients, and these proteins displayed significant correlations with ERVW-1 in schizophrenia." (PMID 37376599, 2023). "In conclusion, ERVW-1 induced ER stress by suppressing GANAB expression, thereby upregulating the expression of ATF6 and XBP1 and ultimately contributing to the development of schizophrenia." (PMID 37376599, 2023). "Furthermore, we visualized the multiple correlations and regression analyses among ERVW-1, GANAB, ATF6, and XBP1 in the serum of individuals with recent-onset schizophrenia (n = 39) using a heatmap." (PMID 37376599, 2023). "Although GANAB is a biomarker of neurological diseases, including MS and traumatic brain injury, its potential as a biomarker of schizophrenia has not been reported." (PMID 37376599, 2023). "However, there are no available studies on the mechanism of GANAB in schizophrenia." (PMID 37376599, 2023). "However, the relationship among GANAB, ATF6, and schizophrenia has not been reported, and there is insufficient evidence to establish a correlation between UPR and schizophrenia." (PMID 37376599, 2023).
synovitis (1 paper, 2020). Inflammation of a synovial membrane. "Although ERp29, PDIA4, Protein ERGIC-53 and GANAB proteins were highly positively correlated in our work with the histological inflammatory score, their presence and their role in the pathophysiology of synovitis have not yet been described." (PMID 32887899, 2020).
cancer (11 papers, 2012 to 2025). A tumor composed of atypical neoplastic, often pleomorphic cells that invade other tissues. "The second μ-17-specific cancer-associated module comprises endoplasmic reticulum (ER) molecular chaperones (PDIA4, PDIA6, GANAB) and heat shock proteins (HYOU1, HSPA5, DNAJB11)." (PMID 41373892, 2025). "To investigate the potential roles of the GANAB in cancer, we conducted correlation analyses of the gene expression and cancer attributes, including tumor grade, stage, recurrent somatic mutations, copy number alterations,and multiple gene signature scores." (PMID 35879690, 2022). "Despite the low tissue and cancer specificity of GANAB, the latter evidenced prognostic ability in liver and urothelial tumors." (PMID 35806376, 2022). "Furthermore, the anti-cancer effect is due to the GANAB inhibition, affecting enhanced glycoprotein turnover, which is reflected by an extremely active lysosomal system and membrane trafficking in tumors." (PMID 35806376, 2022). "Impaired alternative splicing of UBE2F, GANAB or OGDH in vivo may be important for cancer initiation or progression." (PMID 32664474, 2020).